MIR3134 (microRNA 3134)
Synonyms: hsa-mir-3134
Gene: MicroRNA gene on chromosome 3 (15,697,298 to 15,697,371, reverse strand). Ensembl gene ENSG00000264354.
Homologues: Orthologues: chimpanzee MIR3134 (100% identical).